FKBP5 (FKBP prolyl isomerase 5)
Diseases named in the same sentence as FKBP5 in open-access papers (continued):
Sharing a sentence is not in itself a finding about the gene and the disease.
Insulin resistance (continued). "It was observed that chronic hypercortisolism induced methylation of CpG sites on intron 2 of FKBP5, and patients with T2D, obesity, and insulin resistance show the same methylation pathway." (PMID 37512517, 2023). "FKBP5 has been demonstrated to positively regulate the stress response and drive acquisition of metabolic disorders including obesity, insulin resistance, and diabetes." (PMID 36303554, 2022). "Whereas these two previous studies linked PCOS to SNPs in genes related to glucose metabolism and insulin resistance, we focused on FKBP5, which is known to function as an androgen receptor." (PMID 35787810, 2022). "Preclinical studies in animal models have shown that gene deletion or pharmacological inhibition of FKBP5 leads to reduced white adipose tissue mass, and protection from diet-induced weight gain, insulin resistance and hepatic steatosis." (PMID 35817784, 2022). "VSG also leads to decreased accessibility in genes related to insulin resistance and type 2 diabetes, such as Scd1, Serpine1, and Fkbp5, and these changes are found in specific adipocyte subtypes." (PMID 34972124, 2021). "In further studies a link between FKBP5 and insulin resistance, triglyceridemia, obesity, and diabetes has been described." (PMID 32860562, 2020). "In humans, adipose tissue FKBP5 expression and insulin resistance increase with dexamethasone exposure." (PMID 29951131, 2018). "We show that FKBP5 gene expression has strong links to insulin resistance, and that it displays a tendency of elevation in T2D subjects." (PMID 30032404, 2018). "Furthermore, in mice exposed to a chronic high-fat diet, which induces insulin resistance, hypothalamic FKBP5 expression was found to be enhanced, indicating that FKBP5 senses metabolic stressors including nutrient environment." (PMID 38786025, 2024). "Higher percentage methylation of the two FKBP5 CpG sites correlated with adiposity (body mass index and waist circumference), insulin resistance (homeostasis model for insulin resistance, fasting insulin and plasma adipokines) and systemic inflammation (c-reactive protein) in both adipose depots." (PMID 32958048, 2020). "FKBP5 has been linked to metabolic dysfunction including regulation of body weight after bariatric surgery and insulin resistance in non-diabetic individuals." (PMID 29951131, 2018). "Furthermore, FKBP5 mRNA negatively associated with markers of adiposity, insulin resistance and systemic inflammation in GSAT, but not in ASAT." (PMID 32958048, 2020). "Regardless of insulin resistance, the two groups of women with morbid obesity showed upregulation of LYPD8 and downregulation of a greater number of genes, such as REG1B, GKN2, LPL, PNLIPRP2, FKBP5, and CD86, that are related to responses to bacterial stimuli and antimicrobial activity." (PMID 35625760, 2022).
Obesity (22 papers, 2018 to 2026). Accumulation of substantial excess body fat. "Additional studies are required to assess the longitudinal association of FKBP5 with obesity and associated co-morbidities in large population-based samples." (PMID 32958048, 2020). "Studies on the FKBP5 functional rs1360780 SNP (C/T) have shown that the presence of the T allele may influence susceptibility to obesity and metabolic disease." (PMID 35817784, 2022). "FKBP5 is also epigenetically regulated and two independent studies, conducted in peripheral blood and subcutaneous adipose tissue, reported an association between intronic FKBP5 hypermethylation and several obesity and cardiometabolic traits." (PMID 35817784, 2022). "In the context of metabolism, Fkbp5 KO mice are resistant to diet-induced obesity and exhibit elevated glucose and insulin tolerance under high-fat diet (HFD) condition." (PMID 37726498, 2024). "Accordingly, we firstly aimed to investigate abdominal and gluteal adipose tissue DNA methylation of FKBP5 in response to a 12-week exercise intervention in Black African women with obesity." (PMID 35817784, 2022). "In conclusion, we showed that a 12-week exercise intervention induced FKBP5 hypermethylation in a cohort of women with obesity." (PMID 35817784, 2022). "Given that PCOS patients show symptoms like endocrine disorders, metabolic disorders, and obesity, we were interested in exploring potential relationships between FKBP5 and androgens in the context of PCOS etiology." (PMID 35787810, 2022). "Our study findings provide the first demonstration of an association between FKBP5 methylation in intron 7 in SAT and established markers of obesity and metabolic risk." (PMID 32958048, 2020). "Lastly, the molecular function of FKBP5 in adipose tissue during the progression of obesity remains to be elucidated." (PMID 32958048, 2020). "FKBP5 helps the GM address inadequate immunological responses, including lower gut and liver CD11b+Ly6C+ monocytes and neutrophils, and protects against obesity by improving the GM response to HFD-induced MASLD." (PMID 41699049, 2026). "Expression of the Fkbp5 gene is associated with reduced glucose uptake and acts as a negative regulator of the protein kinase B (PKB) pathway, leading to impaired insulin signaling, which is expected to prevent high-fat diet-induced obesity." (PMID 39409181, 2024). "Furthermore, the current study investigated the impact of exercise on FKBP5 methylation in multiple adipose tissue depots, the primary affected organ during obesity development, compared to other studies which used peripheral blood." (PMID 35817784, 2022). "We observed a decrease in Fkbp5 in muscle tissues of sarcopenic obesity mice." (PMID 33534778, 2021). "Elevated FKBP5 expression contributes to HPA dysfunction and associated diseases, including diabetes and obesity." (PMID 34692682, 2021). "Based on this, we propose a model whereby obesity- and inflammation-induced downregulation of GR, and possible induction of GRβ, may augment FKBP5 methylation and, consequently, reduce FKBP5 transcription in GSAT." (PMID 32958048, 2020). "Indeed, preclinical studies using animal models have demonstrated that deletion of the FKBP5 gene protects mice from diet-induced obesity and hepatic steatosis, and pharmacological inhibition of FKBP5 improves their metabolic health." (PMID 32958048, 2020). "Moreover, STAT3, MCL1, PMAIP1, SOD2, FOXO3, FOS, FKBP5 may play an essential role in the genesis and growth of obesity and might serve as a possible therapeutic target." (PMID 34712134, 2021). "We present novel pilot data that shows exercise training induced genotype-specific hypermethylation of FKBP5, an important regulator of the HPA axis, in GSAT and ASAT from South African women with obesity." (PMID 35817784, 2022).
Obesity (continued). "Another research suggested that mice lacking FKBP5 gene had reduce body weight and were resistant to diet-induced obesity, and knockdown of FKBP5 in 3T3-L1 cells had a strong anti-adipogenic impact." (PMID 36397714, 2023). "Mice lacking the FKBP5 gene have reduced bodyweight compared to wildtype mice and are resistant to diet-induced obesity." (PMID 30032404, 2018). "Moreover, in contrast to most DNA methylation studies in obesity, we assessed GR and FKBP5 methylation levels in adipose tissue rather than peripheral blood." (PMID 32958048, 2020).
schizophrenia (21 papers, 2017 to 2025). A major psychotic disorder characterized by abnormalities in the perception or expression of reality. "For instance, individuals carrying the FKBP5 rs1360780 risk variant have been documented to be at increased risk of developing psychiatric disorders including schizophrenia and PTSD." (PMID 36891528, 2023). "This stays in line with a previous study showing that carrying the rs3800373 G allele of the FKBP5 gene is associated with a higher risk for schizophrenia development." (PMID 35329940, 2022). "In another study, a variant of the FK506 binding protein 5 (FKBP5) gene interacted with childhood trauma and affected attention in both schizophrenia patients and healthy controls." (PMID 30983960, 2019). "In one study, the FKBP5 gene polymorphisms were studied with respect to cognitive performance in patients with schizophrenia and healthy controls." (PMID 28822116, 2018). "FKBP5 overexpression was found in different regions of the postmortem brains, which are associated with Alzheimer’s disease and schizophrenia." (PMID 28358316, 2017). "FKBP5 allelic variations have been associated with schizophrenia." (PMID 39272997, 2024). "Another study revealed that variation in the FKBP5 gene (the rs1360870 polymorphism) might impact scores of the RBANS attention domain in patients with schizophrenia and matched controls as well as global cognition only in the group of patients with schizophrenia." (PMID 33255215, 2020). "Compared to healthy controls, increased FKBP5 mRNA expression has been identified in the prefrontal cortex of people with schizophrenia and bipolar disorder." (PMID 40149476, 2025). "In postmortem brain, FKBP5 expression is higher in patients with schizophrenia and depression, especially in upper layer excitatory neurons and FKBP51 has been proposed as an interesting drug target for a subset of patients." (PMID 38317011, 2024). "Clozapine is the only FDA-approved drug for treating resistant schizophrenia (TRS), and several variants, such as FKBP5 variants, have been involved in clozapine response." (PMID 37398599, 2023). "In Cohort 1, FKBP5 gex was more positively correlated with age in schizophrenia subjects vs controls and the ageing trajectory was significantly heightened in the schizophrenia subjects compared to controls (P = 0.0174, FDR = 0.0232)." (PMID 36729133, 2023). "FKBP5 gex was substantially higher in the excitatory neuron group in schizophrenia (+ 32%, t = 2.969, P = 0.00426, FDR = 0.00746)." (PMID 36729133, 2023). "Altogether, these results support that FKBP5 gex and protein levels are increased in psychiatric cases vs controls, with the most pronounced effects seen in schizophrenia subjects." (PMID 36729133, 2023). "In Cohort 5 (BA11, schizophrenia vs control n = 69), FKBP5 gex was higher in schizophrenia vs controls in all cell-type groups except inhibitory neurons (output of all comparisons in Online Resource)." (PMID 36729133, 2023). "The role of the interaction between the FKBP5 gene and stressful life events in the pathophysiology of schizophrenia: a narrative review." (PMID 35223250, 2022). "Previous schizophrenia FKBP5 expression studies showed up-regulation in a subgroup of the brain regions, while others showed no differential expression." (PMID 33673722, 2021). "The significant positive correlation provides an indirect support to the association between childhood trauma and the up-regulation of both IL6 and FKBP5 in the patients with schizophrenia included in our meta-analysis." (PMID 33673722, 2021). "FKBP5 was detected among the top up-regulated genes across the five disorders, and it was most significantly up-regulated in schizophrenia." (PMID 33673722, 2021). "Several studies have explored FKBP5 differential expression patterns in post mortem brain samples of individuals with schizophrenia." (PMID 33673722, 2021).
schizophrenia (continued). "Increased expression of the FKBP5 gene has been demonstrated in the hippocampus and prefrontal cortex of patients with schizophrenia." (PMID 33255215, 2020). "Subsequent analysis of FKBP5 gex in the excitatory neuron sub-clusters showed that this increase was specific to the Exc_L2-3 cluster representing LII–III excitatory neurons, with a striking + 37% higher FKBP5 gex in these neurons in schizophrenia vs controls (t = 3.256, P = 0.00186, FDR = 0.0093)." (PMID 36729133, 2023). "We replicated this finding in an independent sample (Cohort 2, n = 169) using a different method (exon arrays), and found higher FKBP5 gex in cases vs controls overall (t = 3.325, P = 0.001117), again driven by the schizophrenia subjects (t = 3.348, P = 0.00112, FDR = 0.00336)." (PMID 36729133, 2023). "GCs significantly induct the FKBP5-rs1360780 with clozapine consumption in schizophrenia patients." (PMID 37398599, 2023). "It was suggested that confounders, including medication usage, such as chlorpromazine, could influence FKBP5 methylation and expression in schizophrenia patients." (PMID 37398599, 2023). "Similarly to our findings in schizophrenia, FKBP5 was shown to be up-regulated in post mortem brain samples of patients with PTSD, major depressive and bipolar disorders." (PMID 33673722, 2021). "Thus, additional work is needed to fully examine the potential of FKBP5 expression in peripheral blood as a biomarker in schizophrenia." (PMID 33673722, 2021). "Taking into account the body of studies supporting the role of FKBP5 in pathophysiology of stress-related disorders, including schizophrenia, future studies could consider the FKBP5 gene as a potential target for the treatment of psychosis." (PMID 33925151, 2021). "While FKBP5 was found to be up-regulated in schizophrenia, NR3C1 was detected to be down-regulated." (PMID 33673722, 2021). "Fkbp5 was further discussed to have a role in schizophrenia." (PMID 30581382, 2018). "Also some human postmortem brain studies show a correlation of increased FKBP5 expression with psychiatric disease, including bipolar disorder, autism, schizophrenia and alcohol abuse in different brain regions such as the frontal cortex, the cerebellum and the hippocampus." (PMID 36729133, 2023). "Thus, while there is evidence for up-regulation of FKBP5 in post mortem brain samples of individuals with schizophrenia, the results are inconsistent and the differential expression pattern might vary in different brain regions." (PMID 33673722, 2021). "For example, methylation of NR3C1, BDNF, and FKBP5 can differentiate subtypes of MDD, PTSD, or schizophrenia, help to identify stress-responsiveness compared with neurodevelopmental forms of illness, and be used as predictors of risk and resilience." (PMID 41234420, 2025). "We conducted a systematic gene expression meta-analysis of FKBP5 and NR3C1 in cerebellum samples of individuals with schizophrenia vs. healthy controls." (PMID 33673722, 2021). "FKBP5 and NR3C1 differential expression was examined using a publicly available gene expression dataset of whole blood samples of 13 patients with schizophrenia and 8 controls." (PMID 33673722, 2021). "We detect up-regulation of FKBP5 and down-regulation of NR3C1 in the cerebellum of the individuals with schizophrenia." (PMID 33673722, 2021). "FKBP5 and IL6 show significant positive correlation of their expression patterns in the patients with schizophrenia in two out of the three datasets included in our meta-analysis." (PMID 33673722, 2021). "The majority of studies addressing G × E interactions in schizophrenia spectrum phenotypes and BD have focused on the effect of variation in the COMT, BDNF, and FKBP5 genes, showing interactions with cannabis use and childhood trauma." (PMID 28822116, 2018). "We identified consistently heightened FKBP5/1 levels in psychopathology and with age, but not genotype, with these effects strongest in schizophrenia." (PMID 36729133, 2023).
schizophrenia (continued). "In addition, in order to explore a potential role of FKBP5 and NR3C1 as biomarkers, we performed differential expression analysis of the two genes using a blood samples cohort of 13 individuals with schizophrenia and 8 controls." (PMID 33673722, 2021). "Therefore, in this study, we aimed to assess the level of FKBP5 methylation in patients with FEP, acutely relapsed schizophrenia (SCZ-AR) patients, and healthy controls." (PMID 33255215, 2020). "Although higher expression of the FKBP5 gene has been observed in patients with schizophrenia, methylation of this gene has not been investigated in this group of patients." (PMID 33255215, 2020). "In summary, in a systematic meta-analysis we detect up-regulation of FKBP5 and down-regulation of NR3C1 in cerebellum samples of individuals with schizophrenia, and negative correlation between their expression patterns." (PMID 33673722, 2021). "In an additional large sample group of the CommonMind Consortium (CMC; 258 schizophrenia vs. 279 control Dorso-lateral prefronal cortex (DLPFC) samples), FKBP5 was not differentially expressed (p-value = 0.55; CMC FKBP5 differential expression was explored through the SZDB2.0 database)." (PMID 33673722, 2021). "While we did not detect differential expression of FKBP5 or NR3C1 in peripheral blood of patients with schizophrenia when compared to healthy controls, it should be noted that the analysis was performed on a single gene expression dataset (13 schizophrenia vs. 8 controls)." (PMID 33673722, 2021).